CACNG5 (calcium voltage-gated channel auxiliary subunit gamma 5)
Description:
Regulates the gating properties of AMPA-selective glutamate receptors (AMPARs). Modulates their gating properties by accelerating their rates of activation, deactivation and desensitization. Displays subunit-specific AMPA receptor regulation. Shows specificity for GRIA1, GRIA4 and the long isoform of GRIA2. Thought to stabilize the calcium channel in an inactivated (closed) state (By similarity).
Tractability: Small molecule: an approved drug acts on it; a high-quality ligand is known; it belongs to a druggable protein family. Antibody: UniProt predicts a signal peptide or a membrane-spanning region; its Gene Ontology location is reachable by antibodies, with medium confidence.
Gene: Protein-coding gene on chromosome 17 (66,835,117 to 66,894,751, forward strand). Ensembl gene ENSG00000075429.
Subcellular location: Membrane; Postsynaptic density membrane
Gene Ontology:
Molecular function: channel regulator activity; monoatomic ion transmembrane transporter activity; voltage-gated calcium channel activity
Biological process: positive regulation of synaptic transmission, glutamatergic; postsynaptic neurotransmitter receptor diffusion trapping; regulation of AMPA receptor activity; transmission of nerve impulse; calcium ion transmembrane transport; calcium ion transport; monoatomic ion transmembrane transport
Cellular component: glutamatergic synapse; AMPA glutamate receptor complex; postsynaptic density; postsynaptic density membrane; membrane; postsynaptic membrane
Genetic constraint (gnomAD): Loss-of-function variants: 18 observed, 25.77 expected, observed/expected ratio (o/e) 0.7, 90% interval 0.48 to 1.04. The upper end of that interval is the gene's LOEUF score, 1.04, which puts it in group 4 of 6, group 1 being the genes least tolerant of losing a copy. Missense variants: 349 observed, 384.55 expected, observed/expected ratio (o/e) 0.91, 90% interval 0.83 to 0.99. Synonymous variants: 157 observed, 155.95 expected, observed/expected ratio (o/e) 1.01, 90% interval 0.88 to 1.15.
Homologues: Orthologues: chimpanzee CACNG5 (100% identical), macaque CACNG5 (99% identical), dog CACNG5 (97% identical), mouse Cacng5 (97% identical), rat Cacng5 (97% identical), tropical clawed frog cacng5 (94% identical), zebrafish cacng5a (90% identical), zebrafish cacng5b (90% identical), pig CACNG5 (88% identical), rabbit CACNG5 (84% identical), Drosophila melanogaster stg1 (32% identical), Caenorhabditis elegans stg-1 (27% identical). Paralogues in human: CACNG7 (69% identical), CACNG2 (33% identical), CACNG3 (32% identical), CACNG8 (31% identical), CACNG4 (31% identical).
Diseases named in the same sentence as CACNG5 in open-access papers:
CACNG5 is named in the same sentence as 6 diseases in open-access papers, as found by Europe PMC text mining. Sharing a sentence is not in itself a finding about the gene and the disease. The quoted sentences say what the papers report.
schizophrenia (2 papers, 2018 to 2021). A major psychotic disorder characterized by abnormalities in the perception or expression of reality. "There’s evidence demonstrating that CACNG5 is expressed in brain tissues, and the mutation of CACNG5 is associated with schizophrenia, and CACNG5 is also involved in the development of spinal cord ependymoma by regulating MAPK signaling pathway." (PMID 30486773, 2018).
cancer (1 paper, 2022). A tumor composed of atypical neoplastic, often pleomorphic cells that invade other tissues.
CACNG5 also shares sentences with these, for which no sentence is quoted: Anxiety (1 paper); neurodevelopmental disorder (1); Parkinson disease (1); spinal cord ependymoma (1).